MT1HL1 (metallothionein 1H like 1)
Description:
Metallothioneins have a high content of cysteine residues that bind various heavy metals; these proteins are transcriptionally regulated by both heavy metals and glucocorticoids.
Synonyms: MT1P2
Tractability: PROTAC: ubiquitination databases record sites on it.
Gene: Protein-coding gene on chromosome 1 (237,004,103 to 237,004,441, reverse strand). Ensembl gene ENSG00000244020.
Gene Ontology:
Molecular function: metal ion binding
Biological process: cellular response to cadmium ion; cellular response to copper ion; cellular response to zinc ion; detoxification of copper ion; intracellular zinc ion homeostasis
Cellular component: cytoplasm; nucleus
Genetic constraint (gnomAD): Loss-of-function variants: 7 observed, 5.26 expected, observed/expected ratio (o/e) 1.33, 90% interval 0.73 to 1.9. That is too few expected variants to judge how well the gene tolerates losing a copy. Missense variants: 79 observed, 78.77 expected, observed/expected ratio (o/e) 1, 90% interval 0.83 to 1.21. Synonymous variants: 32 observed, 30.98 expected, observed/expected ratio (o/e) 1.03, 90% interval 0.78 to 1.39.
Homologues: Orthologues: chimpanzee MT1HL1 (97% identical), zebrafish mt2 (61% identical). Paralogues in human: MT1H (95% identical), MT1G (89% identical), MT2A (89% identical), MT1A (87% identical), MT1F (85% identical), MT1X (85% identical), MT1B (84% identical), MT1M (77% identical), MT3 (69% identical), MT4 (61% identical), MT1E (52% identical).
Diseases named in the same sentence as MT1HL1 in open-access papers:
MT1HL1 is named in the same sentence as 2 diseases in open-access papers, as found by Europe PMC text mining. Sharing a sentence is not in itself a finding about the gene and the disease. The quoted sentences say what the papers report.
cancer (1 paper, 2021). A tumor composed of atypical neoplastic, often pleomorphic cells that invade other tissues. "Additionally, we found that nearly half of these 21 edges involved a protein of the Metallothionein family (i.e. MT1H, MT2A, MT1HL1, MT1X and MT1G), involved in the regulation of transcription factors and in cancers." (PMID 34197603, 2021).
MT1HL1 also shares sentences with these, for which no sentence is quoted: tumor (2 papers).